GZMB (granzyme B)
Diseases named in the same sentence as GZMB in open-access papers (continued):
Sharing a sentence is not in itself a finding about the gene and the disease.
tumor (continued). "These altered metabolites enhance the tumor-killing effects of T-cells, both directly and indirectly, by alleviating T-cell exhaustion and increasing granzyme B secretion." (PMID 40595481, 2025). "To further confirm the role of Rg3 in CD8+T cell activation, we analyzed the expression of perforin and granzyme B (GzmB) in CD8+T cells in tumor microenvironment." (PMID 39247194, 2024). "CD4+ T cells from peripheral and non-tumor tissues expressed lower levels of granzyme B and perforin than paired circulating CD4+ T cells." (PMID 38335302, 2024). "In the tumor microenvironment (TME), the main function of NK cells is to kill tumor cells through perforin (PFP)/granzyme (GZMB) exocytosis and secrete an array of effector cytokines." (PMID 39457520, 2024). "This is a short-chain fatty acid that, in low concentration, enhances the activity of tumor-infiltrating CD8+ cytotoxic T lymphocytes and, in synergy with the probiotic Bifidobacterium bifidum, causes increased production of granzyme B." (PMID 38715617, 2024). "But we lack further detection of immune response molecules in TME, such as perforin and granzyme B, which limiting the elaboration of tumor prevention mechanisms." (PMID 38439023, 2024). "Granzyme B, one of main cytolytic granule contents encoded by Gzmb, was up-regulated by CGA in the T-cell containing tumor tissues of the two tumor-bearing mice models (p < 0.01, p < 0.05)." (PMID 38164171, 2024). "GZMB-induced cell death is a key mechanism by which CTLs and NK cells eliminate harmful cells including allogeneic, virus-infected, and tumor cells." (PMID 39643914, 2024). "Upon encountering, CD8+ T cells perforate tumor cell membranes and unleash granzyme B into the cytoplasm, or alternatively Fas-expressed tumor cells are susceptible to be eliminated by Fas-L-enriched T cells, both initiating apoptosis." (PMID 38685033, 2024). "Firstly, IL-12 can activate T cells and NK cells to drive Th1 differentiation of CD4+ T cells via enhanced production of IFN-γ and augments the cytolytic ability of NK and CD8+ T cells towards tumor cells via granzyme B and perforin secretion." (PMID 38548896, 2024). "Evidence suggests that the granzyme B tracer is a valuable tool for characterizing the tumor-killing function in the context of immunotherapy." (PMID 39072335, 2024). "This can be partly attributed to the fact that GZMB expression was relatively low in these tumor specimens which introduces relatively high variability in GZMB+ cell counts between serial sections, resulting in a high CV." (PMID 38605049, 2024). "Initially, we observed that CD8+ T cells were predominantly localized in the tumor region, while Granzyme B+ cells were primarily distributed in the stromal region." (PMID 38799432, 2024). "This includes the secretion of Interferon-gamma (IFN-γ), GZMB, and other factors, ultimately leading to tumor cell lysis." (PMID 39519376, 2024). "Our observation revealed higher proportions of CD68+ cells (P < 0.05) and Granzyme B + cells (P < 0.0001) in stroma compared to tumor." (PMID 38799432, 2024). "We investigated the infiltration of total CD8+T cells and cytotoxic T cells (CD8+ Granzyme B+) within the tumor microenvironment." (PMID 38799432, 2024). "This process enhances the activation of effector CD4+ and CD8+ T cells in both the TDLNs and the tumour, as well as increases leukocyte infiltration and the proportion of IFN-γ and Granzyme B-producing CD8+ T cells in the tumour." (PMID 39337605, 2024). "By instigating DNA damage and mitochondrial dysfunction, GZMB sets off a cascade that culminates in tumor cell death." (PMID 39519376, 2024). "the proportion of apoptotic cells were significantly increased, and the frequency of tumor-infiltrating CD11c+ DCs and GzmB+ T cells was markedly increased in the resected tumors." (PMID 38821980, 2024).
tumor (continued). "Spatial distribution analysis elucidated that proliferative T cells, characterized by Ki67 expression, and Granzyme B-expressing T cells were predominantly located within the tumor epithelium." (PMID 38375478, 2024). "Consistent with elevated activation of T cells and NK cells, enhanced anti-tumor environments were detected in the colon, supported by the significant increase of granzyme B and interferon γ levels in the colon of LPS-primed neutrophil recipients." (PMID 39009886, 2024). "With 3D models of NK/tumor cell interactions, we assessed the extracellular and intracellular levels of granzyme B (GrB), which is one of the major components of lytic granules closely related to the degranulation process." (PMID 39457710, 2024). "We also tested T cell secretion of IFN-λ and granzyme B during co-culture with other HER2-positive tumor cells, including A549, A1847, SKBR3, and MDA-MB-231 cells, and consistently observed a dose-dependent induction of IFN-λ and granzyme B by the bsAb." (PMID 39066446, 2024). "In aggregate, we challenge the idea that PI9 alone is essential for tumor evasion and highlight the importance of redundancy when the primary cytotoxic mechanism, GZMB, is inactivated." (PMID 38307835, 2024). "mHTV-02 vaccination induced significantly stronger T-cell responses and more multifunctional (IFN-γ+ GzmB+) CD8+ T-cell infiltration in the tumor." (PMID 38514186, 2024). "G6PD regulates granzyme B expression in tumor-specific cytotoxic T lymphocytes as a metabolic checkpoint." (PMID 38194707, 2024). "After subsequent IHC staining, an abundance of GZMB + cytotoxic T cells was discovered within the tumor of this mouse, resembling that observed in the dual ICI group." (PMID 38805119, 2024). "Immunofluorescence staining of tumor tissues revealed slightly increased infiltration of granzyme B+ cells in the BLM-treated group compared with that in the vehicle group." (PMID 39106105, 2024). "Granzyme B and perforin are potent anticancer mediators that can control tumor proliferation and spreading." (PMID 38806640, 2024). "Since one of the primary mechanisms of GZMB activation is to directly activate pro-caspase 3 in tumor cells, we confirmed via western blotting that the expression of pro-caspase 3 was not different between NALM6 and NALM6-PI9 and SkOV3-CD19 and SkOV3-CD19-PI9." (PMID 38307835, 2024). "In humans, T-bet and Eomes knock-out in NK cells reduce IFNγ, perforin (Prf) and granzyme B (GrzB) production as well as proliferation, thus impairing NK cells anti-tumor function in tumor-bearing NSG mice model." (PMID 39179536, 2024). "Flow cytometry analysis of tumor infiltrating immune cells showed increased frequency of CD8+ TIL that were granzyme B positive and had greater granzyme B levels compared to all other groups." (PMID 39639338, 2024). "Granzyme B plays a vital role in enabling CD8+ T cells to eliminate cancer cells within the tumor microenvironment." (PMID 38169590, 2024). "Th9/Th17 cells that were transferred to the host in a relayed manner induce tumor killing by releasing granzyme B." (PMID 38515134, 2024). "This process promotes the infiltration of CD8+ T-cells into the tumor core, where they can engage in the cytolytic killing of tumor cells through the release of granzyme B and perforin by effector T-cells." (PMID 38794221, 2024). "TDLN tumor-reactive cells also displayed high levels of granzyme B expression after treatment with either cytokine therapy." (PMID 39112631, 2024). "One study demonstrated that CAR‐T cells mediate the GZMB/GSDME/CASP3 signalling axis to accomplish the pyroptosis of tumour cells." (PMID 38652105, 2024). "The immunofluorescence data showed that the concentration of MAIT cells was higher, the level of the immune exhaustion marker PD1 was lower, and the level of the tumor‐killing function marker GZMB was higher in the patients who responded to immunotherapy." (PMID 38509769, 2024).
tumor (continued). "The therapeutic efficacy of TVQC correlated with significant induction of total and IFNg-producing tumor-antigen-specific CD8 T cells and NKDCs expressing granzyme B, IFNg or both in the tumor when compared to the untreated controls." (PMID 38400189, 2024). "CD8+ TEM can secrete γ‐IFN or granzyme B in a very short time to kill tumor cells after exposure to pre‐inoculated neoantigens, whose proportion increased in all treatment groups, and the FSP‐RZ‐BPH had the highest proportion, reaching 49.3%." (PMID 38308098, 2024). "Upon antigen stimulation, CD8+ T cells can rapidly differentiate into effector cells and produce a multitude of effector cytokines (e.g., IL-2, TNF-α, and IFN-γ) and granzyme B to effectively eliminate tumor cells." (PMID 39519411, 2024). "Since our assays demonstrated that PI9 does not alter the dynamics or the frequency of killing mediated by CAR T cells, we next designed a fluorescent reporter to directly visualize GZMB activity at the single-cell level within tumor cells." (PMID 38307835, 2024). "In humans, NK cells comprise about 5–20% of peripheral blood lymphocytes, and they can directly eradicate the tumor cells by cytolysis, via granzyme B and perforin, or indirectly contribute by inducing an efficient T cell-mediated anti-tumor response." (PMID 39767654, 2024). "This enhanced activity was characterized by an increased production of granzyme B in the tumor site during BRB-mediated chemoprevention of HNSCC." (PMID 38256917, 2024). "Our findings revealed that MH treatment not only increased the infiltration of intratumoral T cells but also enhanced their cytotoxic potential, as shown by the elevated levels of IFN-γ and granzyme-B in purified CD45+ immune cells from tumor tissue." (PMID 38444857, 2024). "We found that GZMA expression was higher in CX3CR1+ CD8+ T cells compared to CX3CR1− CD8+ T cells in both spleen and the tumor while expression of GZMB was equivalent." (PMID 38881188, 2024). "Granzyme B participates in multiple anti‐tumor immune pathways which is an appealing immune‐related biomarker." (PMID 39175888, 2024). "mIF on FFPE samples with antibodies of CD4, CD8α, FOXP3, Granzyme B, and pan CK were applied to analyze the tumor regions of pre- and post-ipilimumab treatment for 4 patients (P6, P7, P4 and P8)." (PMID 38448521, 2024). "In Plasmodium-infected mice, the expression level of PD-1 on effector CD8+ T cells infiltrated into tumor tissues is significantly downregulated, while the expression levels of perforin and granzyme B in CD8+ T cells are significantly upregulated." (PMID 38807760, 2024). "For NK cells in the tumor, an increase in granzyme B was observed in the combination therapy group, whereas NK cells in the spleen showed no significant changes." (PMID 38630304, 2024). "At the same time, we found fewer tumour-specific CD8+ T-cells in the lungs, and lower expression of the activation marker CD43 and GzmB in CD8+ T-cells in the tumour when CXCR3 was blocked compared to untreated IAV infected tumour bearing mice." (PMID 38271469, 2024). "The interaction of granzyme B with perforin produces potent cytolytic functions, leading to tumor cell lysis." (PMID 38806640, 2024). "CTLs partially mediate their cytotoxic effects on tumor cells by secreting the serine protease granzyme B (GZMB), which cleaves and activates the initiator caspases 8 and 10 and the pro-apoptotic protein Bid to trigger apoptosis." (PMID 38228372, 2024). "CD8+ T cells are critical effectors of anti-tumor immunity, eliminating cancer cells by secreting granzyme B and induce apoptosis in target cells." (PMID 38762492, 2024). "Herein, we revealed that ENTPD2 strongly suppressed the production of the cytokines IFN-γ, TNF-α, and Granzyme B by CD8+ T-cell subsets in MC38 tumor tissues." (PMID 38755598, 2024).
tumor (continued). "We also observed that the numbers of tumor-infiltrating granzyme B- or interferon gamma (IFNγ)-producing CD8+ T cells were significantly greater in TOFA-Th9 cells than in untreated Th9 cells." (PMID 39187636, 2024). "IFN‐γ acts as a cytotoxic cytokine together with granzyme B and perforin to initiate apoptosis in tumor cells." (PMID 38379331, 2024). "Again, the HER2-CD3-Fc bsAb efficiently bound to the 4T1-HER2-ECD-IV cells and induced robust T cell cytotoxicity and IFN-λ/granzyme B secretion against the subdomain-IV-expressing tumor cells." (PMID 39066446, 2024). "Similar to the result for T cells, the proportion of granzyme B+ tumor cells and the quantity of granzyme B in tumor cells were increased with the increased concentration of IgG-T-TCE-NY, further proving the cytotoxicity of T cells in co-culture." (PMID 38672132, 2024). "For instance, they can demonstrate direct cytotoxic effects on tumor cells by releasing granzyme B and tumor necrosis-related apoptosis-inducing ligand (TRAIL)." (PMID 38927922, 2024). "Slightly lower levels of T-cell immune inhibitory receptors PD-1, LAG-3, and TIM-3, proliferation, and GZMB were also observed in this patient’s tumor supporting reduced T-cell exhaustion/dysfunction during treatment." (PMID 39318388, 2024). "NK cells can be activated by tumor cells, cytokines [e.g., interleukin (IL)-2, IL-12], natural products (e.g., chitosan) to induce direct lysis of tumor cells through the secretion of toxic molecules [e.g., granzyme B (GZMB) and perforin (PRF1)]." (PMID 39439794, 2024). "B cells possess anti-tumor functions mediated by granzyme B, in addition to their role in antigen presentation and antibody production." (PMID 38386050, 2024). "These hypofunctional T cells with elevated expression of inhibitory receptors fail to produce IFN-γ, TNF-α, granzyme B, and perforin to eliminate tumor cells." (PMID 38321486, 2024). "The study identified a 14 amino acid sequence from Hsp70, termed TKD, sensitizing tumor cells to NK cytotoxic activity, orchestrating GzmB release by activated NK cells and inducing apoptosis in Hsp70 membrane-positive tumor cells." (PMID 38846935, 2024). "Immunohistochemical staining for granzyme B on primary tumor sections corroborated the enhanced CD8α+ T-cell activation in primary tumors upon chitin treatment, albeit only significantly in the 4T1-based model." (PMID 38605414, 2024). "Flow cytometric analysis confirmed that combination therapy significantly enhanced CD8+ T cell infiltration in tumor tissue and the expression of GzmB and IFN-γ." (PMID 38992029, 2024). "When the mouse model was exposed to IBA, there was a reduction in the enhanced cytotoxic T‐cell infiltration induced by anti‐PD‐L1 antibody, a decrease in IFNγ and granzyme B expression, and significant resistance to tumor immunotherapy." (PMID 39503247, 2024). "In this context, the constitutively active STAT6 drives the expression of granzyme A, granzyme B, FasL and IFNγ proteins, which can be critical to donor T cell-mediated anti-tumor (GVT) immunity." (PMID 39796136, 2024). "To evaluate the opposing tumor immune effects of GzmB+ Treg vs GzmB+ Th cells, we determined the ratio of GzmB+FoxP3+/GzmB+FoxP- CD4 T cells." (PMID 38968186, 2024). "At the same time, Judy Lieberman's team showed similar results: the cell-killing enzyme Granzyme B can directly cleave GSDME, causing pyroptosis of cancer cells, further activating the anti-tumor immune response and inhibiting tumor growth." (PMID 38323315, 2024). "In response to this migration, CD8+ T cells enable apoptosis in tumor cells through the secretion of effector cytokines such as granzyme B (cytotoxic effect), resulting in an effective antitumor effect." (PMID 39769501, 2024). "MUC16 deletion induced an increase in the proportion of perforin+ and granzyme B+ cells in the T cells, suggesting that the presence of MUC16 is associated with the dysfunction of T cells in the tumor microenvironment of NPC." (PMID 39219440, 2024).
tumor (continued). "As a potent representative of the anti-tumor immune response, granzyme B is considered a potential predictive biomarker for cancer therapy." (PMID 39072335, 2024). "For the tumor explants treated with the anti-PD-1 mAb, five out of the 12 tumor explants responded, as evidenced by an increased percentage of granzyme B-positive CD8 + T cells." (PMID 38637902, 2024). "An upregulation of GZMB expression in tumor-infiltrating CD8+ T cells was detected in tumors treated with Z36-MP5, as well as the activation markers CD69, IFN-γ, CD25 and CD107, whose expression was augmented by combinatorial treatment with anti-PD-1." (PMID 38461299, 2024). "SUV39H1 inhibition led to increased expression of granzyme B, perforin, FasL, and IFNγ, while a number of tumor-infiltrating CTLs remained unchanged in MC38 and CT26 colon tumor models." (PMID 39519018, 2024). "For example, the significantly improved clinical prognosis of patients with proficient mismatch repair (pMMR) CRC is correlated with the extent of CD4+GzmB+ T-cell infiltration in the center of the tumor." (PMID 38515134, 2024). "Perforin first forms pores in the tumor cell membrane, followed by Granzyme B triggering an apoptosis cascade, thus implementing their cytotoxic effects." (PMID 39354474, 2024). "To assess the cytotoxic potential of CD4+ and CD8+ pancreatic TILs, we measured the expression of the cytolytic molecules granzyme B and perforin in T cells isolated from both tumor and patient PBMCs." (PMID 38335302, 2024). "Both IFNγ and GZMB are well known for their direct cytotoxic effects on tumor cells and being able to stimulate production of immune-stimulating cytokines." (PMID 39618825, 2024). "The putatively tumor-reactive DP CD8+ T cells presented lower levels of granzyme B and coexpressed less granzyme B and perforin than DN and SP CD8+ T cells." (PMID 38335302, 2024). "As a result, granzyme B and activated caspases lead to membrane blebbing, DNA damage, and eventually the lysis of tumor cells." (PMID 38339258, 2024). "Flow cytometry of isolated tumor-infiltrating immune cells and splenocytes showed a notable increase in granzyme B within CD8+ T cells in both the TLR5 agonist monotherapy and combination therapy groups." (PMID 38630304, 2024). "A significant increase (2.6-fold) in the expression of IFN-γ (p = 0.0148) and granzyme B (p = 0.0261) was also observed at the level of the whole tumor tissue." (PMID 38444857, 2024). "The elevated levels of granzyme B+ B cells in tumor samples resulted from tumor cell chemotaxis through the MIF- (CD74 + CXCR4) signaling pathway." (PMID 38386050, 2024). "Supporting this, the proportion of CD8+ tumor-infiltrating lymphocytes (TILs) expressing IFN-γ or GZMB, which was increased by LA treatment, was markedly decreased by AMPKα loss in immunocompetent mice." (PMID 39545415, 2024). "CD103+ TRM cells can directly kill epithelial-derived tumor cells by producing a large number of cytotoxic particles and cytokines, such as granzyme-B, perforin, and IFN-γ." (PMID 38384466, 2024). "Cytotoxic CD8+ T cells play a critical role in eliminating tumor cells by producing Granzyme B (GzmB) and effector cytokines such as IL-2, TNF-α, and IFN-γ." (PMID 38750022, 2024). "This reduction was associated with increased expression of inflammatory cytokines, especially granzyme B and perforin, both of which are known to be important for anti-tumor immune responses." (PMID 39234236, 2024). "In the tumor, in contrast to the TdLN, there was a robust population of Ly6A+ GzmB+ cells in all groups including controls." (PMID 38496632, 2024). "The numbers of TILs per gram tumor secreting GzmB, IFNγ, TNFα, and IL-2 were considerably higher in both primary and secondary tumor in the hRT/lena treatment group." (PMID 38646638, 2024).